UNC13B (unc-13 homolog B)
Description:
Plays a role in vesicle maturation during exocytosis as a target of the diacylglycerol second messenger pathway. Is involved in neurotransmitter release by acting in synaptic vesicle priming prior to vesicle fusion and participates in the activity-depending refilling of readily releasable vesicle pool (RRP) (By similarity). Essential for synaptic vesicle maturation in a subset of excitatory/glutamatergic but not inhibitory/GABA-mediated synapses (By similarity). In collaboration with UNC13A, facilitates neuronal dense core vesicles fusion as well as controls the location and efficiency of their synaptic release (By similarity).
Synonyms: munc13; UNC13; hmunc13; Unc13h2; Munc13-2
Tractability: Antibody: UniProt places it where antibodies can reach, with medium confidence; its Gene Ontology location is reachable by antibodies, with medium confidence. PROTAC: ubiquitination databases record sites on it; its protein half-life has been measured.
Gene: Protein-coding gene on chromosome 9 (35,161,829 to 35,405,339, forward strand). Ensembl gene ENSG00000198722.
Subcellular location: Cytoplasm; Membrane; Cell membrane; Synapse
Subcellular location (Human Protein Atlas): Vesicles; Golgi apparatus; Intermediate filaments; Nucleoplasm
Pathways (Reactome):
Neuronal System: Acetylcholine Neurotransmitter Release Cycle; Dopamine Neurotransmitter Release Cycle; Glutamate Neurotransmitter Release Cycle; Norepinephrine Neurotransmitter Release Cycle; Serotonin Neurotransmitter Release Cycle
Gene Ontology:
Molecular function: GTP-dependent protein binding; protein binding; calmodulin binding; diacylglycerol binding; small GTPase binding; syntaxin-1 binding; calcium ion binding; phospholipid binding
Biological process: acrosomal vesicle exocytosis; cellular response to glucose stimulus; positive regulation of apoptotic process; positive regulation of protein secretion; chemical synaptic transmission; dense core granule priming; neuronal dense core vesicle exocytosis; positive regulation of inhibitory postsynaptic potential; positive regulation of synaptic vesicle priming; synaptic transmission, glutamatergic; synaptic vesicle priming
Cellular component: cytosol; Golgi apparatus; membrane; neuromuscular junction; plasma membrane; presynaptic active zone; presynaptic membrane; synaptic vesicle membrane; terminal bouton; cytoplasm; synapse
Genetic constraint (gnomAD): Loss-of-function variants: 134 observed, 210.72 expected, observed/expected ratio (o/e) 0.64, 90% interval 0.55 to 0.73. The upper end of that interval is the gene's LOEUF score, 0.73, which puts it in group 3 of 6, group 1 being the genes least tolerant of losing a copy. Missense variants: 1,723 observed, 2,044.8 expected, observed/expected ratio (o/e) 0.84, 90% interval 0.81 to 0.88. Synonymous variants: 693 observed, 747.2 expected, observed/expected ratio (o/e) 0.93, 90% interval 0.87 to 0.99.
Homologues: Orthologues: chimpanzee UNC13B (99% identical), dog UNC13B (78% identical), pig UNC13B (78% identical), rabbit UNC13B (78% identical), mouse Unc13b (73% identical), rat Unc13b (73% identical), tropical clawed frog UNC13B (31% identical), macaque UNC13B (30% identical), zebrafish UNC13B (27% identical). Paralogues in human: UNC13A (28% identical), UNC13C (25% identical).
Diseases named in the same sentence as UNC13B in open-access papers:
UNC13B is named in the same sentence as 34 diseases in open-access papers, as found by Europe PMC text mining. Sharing a sentence is not in itself a finding about the gene and the disease. The quoted sentences say what the papers report.
epilepsy (3 papers, 2022 to 2023). A brain disorder characterized by episodes of abnormally increased neuronal discharge resulting in transient episodes of sensory or motor neurological dysfunction, or psychic dysfunction. "Trio-based WES has been successful in defining the most likely epilepsy-implicated loci and screening out candidate genes, such as UNC13B, CELSR3, and CDK19 in numerous studies." (PMID 37152436, 2023). "The identified variants in epilepsy patients had mutations in the UNC13B gene, which included one nonsense variant, two variants at or around a splice site, one heterozygous missense variant, and four missense variants which were seen in the familial cases of epilepsy." (PMID 38188011, 2023). "UNC13B, which is closely related to UNC13A, plays a role in autism spectrum disorders (ASD), epilepsy, and schizophrenia." (PMID 38188011, 2023).
partial epilepsy (3 papers, 2023). "Patients with the variant types of UNC13B gene products had partial epilepsy and/or febrile seizures." (PMID 38188011, 2023). "The results seen in the Drosophila study and the seizure study indicated that UNC13B is potentially associated with partial epilepsy." (PMID 38188011, 2023). "Additionally, the UNC13B gene has been linked to the disease formation of partial epilepsy." (PMID 38188011, 2023). "UNC13B, which is closely related to UNC13A, has shown its significance in autism spectrum disorders (ASD), partial epilepsy, and schizophrenia." (PMID 38188011, 2023).
amyotrophic lateral sclerosis (2 papers, 2023 to 2026). Amyotrophic lateral sclerosis (ALS) is a neurodegenerative disease characterized by progressive muscular paralysis reflecting degeneration of motor neurons in the primary motor cortex, corticospinal tracts, brainstem and spinal cord. "In humans, specific variants of the genes UNC13A and UNC13B are associated with the severe degenerative motoneuron disease amyotrophic lateral sclerosis (ALS), as well as with bipolar affective disorder." (PMID 41399760, 2026).
diabetic nephropathy (2 papers, 2010 to 2015). "This is relevant because UNC13b is critical for regulation of glomerular apoptosis and has been recently implicated in the pathology of diabetic nephropathy." (PMID 26106624, 2015). "Of note, this included one CpG site located 18 bp upstream of the transcription start site of UNC13B, a gene in which the first intronic SNP rs13293564 has recently been reported to be associated with diabetic nephropathy." (PMID 20687937, 2010). "While no consistently replicated genetic associations have been identified, various candidate gene associations in diabetic nephropathy in type 1 diabetes (T1D) have been proposed, such as the SNP rs13293564 G/T substitution in intron 1 of UNC13B, and SOD1 SNPs." (PMID 20687937, 2010). "For example, a genome-wide DNA methylation analysis from whole blood of type 1 diabetic patients with or without renal disorders identified hypermethylation of UNC13B promoter in the diabetic nephropathy group." (PMID 26106624, 2015).
Nephropathy (2 papers, 2010 to 2023). A nonspecific term referring to disease or damage of the kidneys. "Conducting an analysis of 21 other markers, which identified the variability of the UNC13B gene, showed consistent associations of the SNP rs13293564 with nephropathy in the three populations." (PMID 38188011, 2023). "Only one SNP, namely rs2281999, which is located in the UNC13B gene, was seen to be significantly associated with nephropathy after correction for multiple testing was performed." (PMID 38188011, 2023). "UNC13B substitutions are also linked to the increased risk of nephropathy in patients with Type 1 Diabetes (T1D)." (PMID 38188011, 2023). "In the presence of hyperglycemia, which is an event occurring early in the development of nephropathy, UNC13B mediates apoptosis in glomerular cells." (PMID 38188011, 2023).
chronic myeloid leukemia (1 paper, 2022). "UNC13B is a potential therapeutic target for patients with arsenic trioxide-resistant chronic myeloid leukemia." (PMID 35707364, 2022). "We aimed to investigate the role and mechanism of the UNC13B gene in K-562 cells, an arsenic trioxide-resistant chronic myeloid leukemia cell line." (PMID 35707364, 2022). "Western blot results confirmed that UNC13B may modulate the apoptosis and proliferation of arsenic trioxide-resistant chronic myeloid leukemia cells through the mediation of MAP3K7, CDK4, and PINK1." (PMID 35707364, 2022).
diabetes (1 paper, 2010). "MUNC13, the protein coded for by UNC13B, has been shown to be up-regulated in the renal cortex of rats with streptozotocin-induced diabetes and its expression is induced by hyperglycaemia." (PMID 20687937, 2010).
multiple myeloma (1 paper, 2025). "Quantitative analysis further confirmed a marked reduction in colony numbers in the shUNC13B group, indicating that UNC13B contributes to the anchorage-independent growth ability of multiple myeloma cells." (PMID 41007649, 2025). "Quantitative real-time PCR (qPCR) was performed to evaluate UNC13B mRNA expression in several human multiple myeloma cell lines, including U266, ARD, and RPMI 8226." (PMID 41007649, 2025). "Given the critical importance of apoptotic dysregulation and treatment resistance in multiple myeloma (MM), we hypothesized that UNC13B may also contribute to MM pathogenesis." (PMID 41007649, 2025). "Collectively, these findings suggest that UNC13B contributes to MM pathogenesis and may serve as a promising therapeutic target in multiple myeloma." (PMID 41007649, 2025). "Our study demonstrates that UNC13B mRNA is upregulated in multiple myeloma cell lines." (PMID 41007649, 2025). "UNC13B may represent a novel therapeutic target in multiple myeloma." (PMID 41007649, 2025). "Collectively, these results indicate that downregulation of UNC13B suppresses cell proliferation, disrupts normal cell-cycle progression, and promotes apoptosis in ARD multiple myeloma cells." (PMID 41007649, 2025). "Collectively, these findings suggest that UNC13B may regulate multiple oncogenic and apoptotic signaling pathways—such as those involving PINK1, CDK2, AKR7A3, and Bim—to promote cell survival and proliferation in multiple myeloma." (PMID 41007649, 2025).
renal carcinoma (1 paper, 2020). A carcinoma arising from the epithelium of the renal parenchyma or the renal pelvis. "While UNC13B and SFXN2 are present in five and four tumor entities, respectively, only for renal cancer are both UNC13B and SFXN2 favorable." (PMID 32599841, 2020).
type 1 diabetes (1 paper, 2023). "Researchers have shown that UNC13B, PFKFB3, FCN1 and SLC11A1 were diagnostic markers for type 1 diabetes." (PMID 36837510, 2023).
type 1 diabetic nephropathy (1 paper, 2010). "One CpG in this list, cg07341907 is located 18 bp upstream of the transcription start site of a previously identified type 1 diabetic nephropathy gene, UNC13B." (PMID 20687937, 2010).
cancer (5 papers, 2020 to 2025). A tumor composed of atypical neoplastic, often pleomorphic cells that invade other tissues. "The results showed that UNC13B levels were significantly increased in ATO-resistant sample compared to para-cancer tissues." (PMID 35707364, 2022). "Similar to UNC13B, studies showing any functional correlation of SFXN2 with cancer progression, developments, etc. are missing." (PMID 32599841, 2020). "For example, high expression of UNC13B is favorable in five and SFXN2 in four different cancer types." (PMID 32599841, 2020). "Within the favorable genes, UNC13B, and SFXN2 cover nine cancer types and in the same way, SLC2A1, PLS3, SLC16A1, and SLC16A3 within the unfavorable set of genes and could serve as novel target structures." (PMID 32599841, 2020). "So far, no function has been described for UNC13B in cancer." (PMID 32599841, 2020).
tumor (5 papers, 2017 to 2025). "Mechanistically, UNC13B may exert tumor-promoting effects by modulating key regulatory proteins, including PINK1, CDK2, AKR7A3, and Bim." (PMID 41007649, 2025). "Mechanistically, UNC13B could influence both the total output and the cargo composition of secretory vesicles, thereby shaping the tumor niche and therapeutic response." (PMID 41007649, 2025). "In the early stage of the current study, UNC13B expression was found to be increased in tumor cells of ATO-resistant patients (data not shown)." (PMID 35707364, 2022). "UNC13B is favorable in five and SFXN2 in four tumor entities, implicating that these genes might have a general prognostic value." (PMID 32599841, 2020).
hematologic malignancies (1 paper, 2025). "Among these, mitochondrial quality control is increasingly recognized as a vulnerability in hematologic malignancies, suggesting that UNC13B may influence MM cell survival partly through mitochondrial dynamics and mitophagy regulation." (PMID 41007649, 2025).
metabolic disorders (1 paper, 2022). "This suggests that the quality control of mitochondria will be significantly affected during UNC13B down-regulation, and the accompanying metabolic disorders will further affect the cell energy metabolism." (PMID 35707364, 2022).
UNC13B also shares sentences with these, for which no sentence is quoted: autism spectrum disorder (2 papers); intellectual disabilities (2); lung carcinoma (2); Anxiety (1); bipolar disorder (1); bone marrow failure (1); chromosomal instability syndrome (1); Chronic Lymphoid Leukemia (1); Fanconi anemia complementation group G (1); hematologic tumor (1); Hyperglycemia (1); hypogammaglobulinemia (1); infection (1); insulinoma (1); mastocytoma (1); melanoma (1); neurodegenerative disease (1); psychiatric disorder (1); schizophrenia (1).